CD4 (CD4 molecule)
Diseases named in the same sentence as CD4 in open-access papers (continued):
Sharing a sentence is not in itself a finding about the gene and the disease.
COVID-19 (continued). "It has been shown that reduced numbers of CD4+ and CD8+ T cells in patients admitted to the intensive care correlated with COVID-19-associated severity and mortality, suggesting that T cells are important for a favorable clinical outcome." (PMID 33293664, 2020). "Afterward, the CD4+ cell count (P = 0.015), NLR (P = 0.032) and D-dimer (P = 0.016) were considered the independent risk factors of the severe COVID-19 cases." (PMID 32985562, 2020). "Such balance is altered in COVID-19 critical patients with expansion of naïve CD4+ T-cell subset and reduced memory cell percentage further showing the severity of the immune system impairment in these subjects." (PMID 32640747, 2020). "Flow cytometric analysis of critically ill COVID-19-infected patients demonstrated that significant lung injury is accompanied by a substantial decrease in the number of CD4+, CD8+ T lymphocytes and NK cells." (PMID 32851877, 2020). "The median proportions of effector CD4+ T cells were significantly lower in COVID-19 X-ray (+) and COVID-19 X-ray (−) patients than in healthy control (2.9% vs. 2.8% vs. 33.2%, p < 0.0001)." (PMID 33291439, 2020). "First, we determined the numbers of CD4+ T cells in the blood of COVID-19 patients and stratified the patients into age groups of 29 to 79 (median, 62) and 80 to 96 (median, 86) years." (PMID 32948688, 2020). "Both CD8+ T cells and CD4+ T cells have elevated levels of the programmed death (PD)-1 receptor in COVID-19 patients, a sign of T cell functional exhaustion." (PMID 32922297, 2020). "There were increased levels of CD69 and HLA-DR/CD38 co-expression on CD8+ and CD4+ T cells in both COVID-19 and malaria patients compared to healthy controls which is characteristic for acute infections." (PMID 32983106, 2020). "An analysis of 452 patients, 286 with severe COVID-19, exhibited a reduction of CD4+, CD8+ and regulatory T lymphocytes, a reduction of monocytes, eosinophils and basophils, and an increase in the neutrophil-to-lymphocyte ratio (NLR)." (PMID 33584667, 2020). "After the onset of COVID-19, CD4+T lymphocytes are immediately activated and become pathogenic type 1 T helper (Th1) cells that produce granulocyte-macrophage colony-stimulating factor, and accelerate the inflammatory response." (PMID 32766268, 2020). "The pathological and anatomical examination of patients with COVID-19 also showed that the number of CD4 and CD8 T-cells was greatly reduced." (PMID 32903644, 2020). "As summarized in, in comparison with six controls, a significantly higher amount of CD4+ T cells from eight COVID-19 patients was able to produce TNF, CD107a, IFN-γ, IL-2, and particularly IL-17 (that showed the highest difference)." (PMID 32632085, 2020). "Virus-specific cTFH cells were a substantial fraction of the SARS-CoV-2-specific CD4+ T cells in acute and convalescent COVID-19 cases." (PMID 33010815, 2020). "Patients with COVID-19, especially with the severe events, developed lymphopenia mainly as a result of decreasing CD4+Th (T helper) cell number." (PMID 32722596, 2020). "Dyspnoea, along with a significantly decreased CD4+ cell count, is likely to occur in the early stage of COVID-19 in patients with hypertension." (PMID 33009426, 2020). "The main player in this cytokine storm, incriminated in COVID-19 as well, is interleukin-6 (IL-6), which is secreted by innate immune cells and monocytes and is also a fine-tuning regulator of CD4+, CD8+ T cells, and B cells and activates monocytes." (PMID 32471171, 2020). "We found that age, CD4 count, time length since HIV diagnosis and treatment status were associated with COVID-19 occurrence among PLWHA." (PMID 32818208, 2020). "Low naive CD4+ T cell percentage correlated with COVID-19 disease severity among acute patients (p = 0.0008), but the relationship was lost when considering all COVID-19 cases (acute and convalescent." (PMID 33010815, 2020).
COVID-19 (continued). "For a description of the activation status, we assessed the frequencies of CD69 and HLA-DR/CD38 on CD8+ and CD4+ T cells in COVID-19 and malaria patients as well as in healthy controls." (PMID 32983106, 2020). "These CD4+ T-cells in COVID-19 patients have higher expression of CD69, CD38 and CD44 compared with healthy controls, indicating their activated status." (PMID 34676125, 2020). "The ratio ofCD4+ T cells was stable, but the composition ofthe CD4+ T cell subset differed significantly betweenthe HCs and COVID-19 patients." (PMID 32377375, 2020). "In this context, it is relevant to note the presence of SARS-CoV-2-reactive CD4+ T cells in recovered COVID-19 patients 65, 66, and that the development of SARS-CoV-2 reactive CD38+/HLA-DR+/CD4+ T cells strongly correlates with a positive clinical outcome." (PMID 33173418, 2020). "Compared with other T-cell subsets, CD8+ TEM, CD8+ TTE, and CD4+ TTE were substantially clonally expanded in the COVID-19 patients, with more expanded clonotypes containing more CD8+ TEM and CD8+/CD4+ TTE." (PMID 32796814, 2020). "This patient was on ARTs, his HIV viral load was low, and his CD4+ cell count was high before he contracted COVID-19." (PMID 32858801, 2020). "It is also possible that increased IL-6 leads to a reduction in CD4+ T cells and NK cells in patients with COVID-19 and immune dysregulation." (PMID 32849623, 2020). "In this report, we found that age, CK level, CD4 count, CD8 count, CD8 %, and C3 count were the independent risk factors for the progression of COVID-19." (PMID 32866109, 2020). "Using the peptide “megapooller” prescribed by HLA class I and II, the research group detected CD8+ and CD4+ T cells specific to SARS-CoV-2 in the blood samples of 70–100% of healing COVID-19 patients." (PMID 32595358, 2020). "The initial inflammation in COVID-19 is propitious to the activation and differentiation of CD4+ and CD8+ T cells." (PMID 32849623, 2020). "In contrast, the proportions of various activated CD4+ T cell subsets among the T cell compartment, including Th1, Th2, and Th17-like cells were increased and more clonally expanded in severe COVID-19 patients." (PMID 33101705, 2020). "Our ex vivo study indicates that COVID-19 patients show a cytotoxic response dominated by CD8+ T cells in contrast to CD4+ T cells during the early period of infection." (PMID 32948688, 2020). "Further, higher risks of in-hospital death from COVID-19 are directly associated with lower counts of T lymphocyte subsets (CD3+, CD4+, and CD8+) and B-cells." (PMID 32916821, 2020). "A previous study regarding lymphocyte subsets indicated that COVID-19 patients had reduced count of total lymphocytes, CD4+ T cells, CD8+ T cells, B cells, and natural killer cells." (PMID 32589691, 2020). "With the help of HLA class II predicted peptide megapools they demonstrated that all COVID-19 patients had robust viral spike glycoprotein (S) specific functional CD4+ T cell response that correlated with magnitude of SARS-CoV2 specific IgG and IgA titers." (PMID 33133083, 2020). "In fact, IL2RA+CD4+ T-cells from severe COVID-19 patients expressed Th1, Th2, and IL-10 signature genes more frequently whereas Th17 differentiation was suppressed in IL2RA+ T-cells from both groups." (PMID 33178221, 2020). "Overall, we saw an increase of CD8+ EM T cells and CD8+ and CD4+ CM T cells in both COVID-19 and malaria compared to healthy individuals." (PMID 32983106, 2020). "A post-treatment decrease in CD8+ T cells and increase in CD4+/CD8+ ratio have been indicated as independent predictors of poor treatment outcomes in COVID-19." (PMID 33375675, 2020). "We noticed a significant reduction of CD4+ effector cells and increase of CD4+ central memory cells, both in COVID-19 X-ray (+) and COVID-19 X-ray (−) compared to healthy group." (PMID 33291439, 2020).
COVID-19 (continued). "At the same time resolution of COVID-19 is associated with activated cellular and humoral responses, particularly presence of antigen specific CD4+ T cells in vast majority of COVID-19 patients that correlate with levels of antigen specific antibody response." (PMID 33133083, 2020). "Longitudinal analysis of immune profiling of COVID-19 finds elevated plasma levels of IL-17A and IL-22 along with increased IL-17 secretion by CD4+ T cells in severe patients, indicative of promotive effects of Th17 cells in COVID-19 progression." (PMID 33584679, 2020). "In COVID-19 patients with pneumonia, we found an increase capability of CD4+ or CD8+ T cells to produce in vitro IL-17, that is able to strengthen the inflammation response and to activate neutrophils." (PMID 32632085, 2020). "The prediction model established upon IL-8 and the number of CD4+ T cells and NK cells has a good value to distinguish the fatal cases from the survived patients among patients with COVID-19." (PMID 32661797, 2020). "After 15-20 days of signals and symptoms, people who recovered from COVID-19 are presenting a reestablishment of their lymphocyte count, with an increase of CD4 T and CD8 T memory cells specific for SARS-CoV-2 protein." (PMID 33426096, 2020). "Looking at the expression of T-bet and eomes in CD8+ and CD4+ T cells in COVID-19 and malaria patients we saw an upregulation of T-bet in COVID-19 and an upregulation of both T-bet and eomes in malaria." (PMID 32983106, 2020). "CD4+ T cells are significantly diminished in severe COVID-19 cases." (PMID 41155463, 2025). "This study provides insights into the collaboration of T and B-cell responses after bivalent ancestral/Omicron BA.1-containing COVID-19 booster vaccination and emphasises the role of memory CD4 T cells and baseline antibody titres in influencing antibody breadth against new viral variants." (PMID 40251187, 2025). "However, the number of CD4+ T cells of sepsis or COVID-19 patients is often lower at 3–4 days after onset." (PMID 41158471, 2025). "Similarly, CD4 naive T cells, monocytes, macrophages M0, activated mast cells and neutrophils were upregulated and CD8 T cells, CD4 memory resting T cells and resting mast cells were downregulated in the COVID-19 patient group." (PMID 39965013, 2025). "Therefore, this study aimed to assess the antibody response following bivalent mRNA COVID-19 vaccine boosters in HIV-infected individuals with CD4 T lymphocyte counts ≤ 200 cells/mm3 compared to those with counts > 200 cells/mm3." (PMID 40299994, 2025). "Taken together, the levels of CD4+ T cells and their main subsets could be crucial for sarcoidosis and COVID-19 development, prognosis, and outcomes." (PMID 41376646, 2025). "Additionally, we evaluated the immunogenicity of an inactivated COVID-19 vaccine booster in PLWH with CD4+ T cell counts ≤500 cells/μL within both 18–59 and ≥60 years age groups." (PMID 40838719, 2025). "Therefore, our goal was to characterize dysregulated CD4+ T cell subsets in the peripheral blood of sarcoidosis patients after acute COVID-19." (PMID 41376646, 2025). "Nine out of the ten combinations that contributed most to the variability fell on the negative axis of PC1, and included TRAV9-2 × TRAJ30 and TRAV26-1 × TRAJ39, which both showed increased proportional usage in the COVID-19 CD4 repertoires compared to healthy controls." (PMID 40331338, 2025). "Furthermore, individuals with low CD4 counts or unsuppressed HIV have weaker immune responses to COVID-19 vaccination and to natural SARS-CoV-2 infection." (PMID 40463375, 2025). "However, other studies have reported diminished responses to COVID-19 vaccination in PLWH with lower CD4+ T cell counts." (PMID 40432125, 2025). "Previous study has shown that SARS-CoV-2-specific CD8+ and CD4+ T cells responses were identified in COVID-19 convalescent patients and may play an important role in recovery." (PMID 39851259, 2025).
COVID-19 (continued). "In their study, IFI44L in B cells, S100A8 in monocytes, and NCR2 in natural killer cells were identified as crucial markers that are involved in the innate immune response of COVID-19, while it was also demonstrated that ZFP36L2 in CD4+ T cells can regulate the inflammatory process of COVID-19." (PMID 40163554, 2025). "Recently, neutrophilia has been described as an indicator of severe respiratory symptoms and a poor prognosis in patients with COVID-19, and a high ratio of neutrophils to CD4+ lymphocytes (NCD4LR) indicates poorer immune function and prolonged viral clearance in this patients population." (PMID 40002608, 2025). "However, the frequency of CD4+TIM-3+ T cells was elevated in COVID-19 compared to HD at baseline (p<0.01)." (PMID 40458413, 2025). "A lower CD4+ T cell count and higher HIV viral load were associated with lower spike (trimer) total Ig titers in vaccinated PLWH, indicating a diminished response to COVID-19 vaccination." (PMID 40432125, 2025). "A coordinated CD4 + T cell, CD8 + T cell, and antibody response is associated with milder COVID-19." (PMID 40624061, 2025). "It has also been reported that reduced CD4+FoxP3+ Tregs are present in COVID-19, but an increased frequency of TIGIT+ Tregs at the time of hospital admission, which correlates with severity, suggesting that a robust suppressive activity is associated with fatal outcomes." (PMID 41488664, 2025). "This could be due to low CD4 T cell count being a marker for less engagement in care or due to these patients dying from something other than COVID-19." (PMID 40779550, 2025). "However, patients with severe or critical COVID-19 demonstrate 2.1- and 2.2-fold reduced absolute counts of CD4+ and CD8+ T cells, respectively, compared to those with moderate disease." (PMID 41376637, 2025). "Moreover, LTBI/COVID-19 individuals predominantly displayed CD4+ and CD8+ T cells with highly polarized, compact mitochondria at baseline, which remained unchanged under stimulation." (PMID 40458413, 2025). "Consequently, PLWH have been prioritized for COVID-19 vaccination, with primary and booster schedules recommended based on CD4+ T cell count and HIV viremia levels in China and other regions (9, –, 11)." (PMID 40838719, 2025). "The study also showed similar dynamic patterns between soluble and membrane-bound counterparts in six patients with critical COVID-19, and flow cytometry revealed higher PD-1 expression on CD4+ and CD8+ T cells in patients with critical disease in compared to moderate state of disease." (PMID 40005306, 2025). "Additionally, this group displayed mainly IFN-γ and CD107a-producing M-specific CD4+ T cells suggesting a protective role for cytotoxic Th1 cells in COVID-19." (PMID 40392230, 2025). "Moreover, COVID-19 played its role in immune dysregulation, characterized by lymphopenia, reduced CD4+/CD8+ T cells, and impaired neutrophil and macrophage function." (PMID 40821274, 2025). "Importantly, through the use of ex vivo lung models, we report M-peptide-responding functional IFN-γ-secreting and proliferating CD4+ T cells in recovering COVID-19+." (PMID 40698364, 2025). "A plausible explanation for higher acute CD4+ T cells and reduced memory CD4+ T cells in pediatric COVID-19 could be that heightened early innate immune responses rapidly reduce viral load, leading to diminished antigen-driven T cell responses over time." (PMID 40906527, 2025). "In this group, the significantly higher CD4+ T cell responses observed 24 weeks after the second booster compared to the non-COVID-19 group may reflect the contribution of natural infection-induced immunity." (PMID 41251472, 2025). "Additionally, COVID-19 and cancer patients who underwent chemotherapy displayed significantly lower frequencies of CD4+ naïve T cells compared to healthy donors of the same age range (between the ages of 40–80)." (PMID 40308557, 2025).
COVID-19 (continued). "A lower CD4+ T cell count (<200 vs. ≥500, β = −0.400, p = 0.033) and higher HIV viral load (≥200–<5000 vs. <200, β = −0.275, p < 0.001) were associated with lower spike (trimer) total Ig titers, indicating a diminished response to COVID-19 vaccination." (PMID 40432125, 2025). "Strengths include thorough profiling of several features and subsets of SARS-CoV-2–specific CD4+ T cells and BMem, the relatively large size of the cohort, and cohort development beginning in spring 2020, prior to the widespread deployment of COVID-19 vaccines." (PMID 40906527, 2025). "Similarly, LTBI/COVID-19 has predominantly CD4+ and CD8+ T cells with highly polarized, compact mitochondria like HD and LTBI, whereas T cells from COVID-19 show highly polarized, fragmented mitochondria." (PMID 40458413, 2025). "Moreover, several researchers indicate an increased risk of TB infection transitioning into TB disease in the context of COVID-19 due to the depletion of CD4 + T cells." (PMID 39997463, 2025). "Additionally, patients with long-term COVID-19 symptoms also showed upregulated caspase-1 activity in CD4+ T-cells." (PMID 40051620, 2025). "Here, we used COVID-19 mRNA vaccination as a model to explore whether long-lasting CD4+ and CD8+ T cell immunity can be generated and modulated through vaccination in INR with severe immune dysfunction." (PMID 41212052, 2025). "Subsequently, CD4 + helper T cells promote the overall adaptive response by recruiting Th1 cells and supporting the differentiation of B lymphocytes to produce specific anti COVID-19 antibodies." (PMID 40495223, 2025). "Similarly, S- and N-peptide responsive CD4+ T cells, with a robust IFNγ response, were detected in PBMCs of COVID-19 convalescent patients." (PMID 41306976, 2025). "In humans, CD4+ TEMRA cells are seen in low frequencies in the blood (0.3–18%) compared to CD8+ TEMRA cells (10–30%), but are associated with protective immunity, notably in COVID-19 and dengue infections." (PMID 40354406, 2025). "The goal of this study is to characterize CD4+ T cell subsets, playing a pivotal role in the regulation of innate and adaptive immunity, in the peripheral blood of patients with sarcoidosis after COVID-19." (PMID 41376646, 2025). "In patients with COVID-19, blood CD4+ lymphocyte values below the cut-off value of 472.5 cells/mm3 may indicate a severe clinical presentation (AUROC: 0.692, sensitivity: 68.4%, specificity: 63.5%, p = 0.001)." (PMID 40718799, 2025). "Despite the significant reduction in absolute T-cell counts a higher proportion of specific CD8+ T cells against SARS-CoV-2 have been reported in patients with mild disease; however, the increase in CD4+/CD8+ ratio has been described in patients with severe COVID-19." (PMID 40303184, 2024). "Moreover, although COVID-19 mRNA vaccines have a strong Th1 induction ability, it is possible that the environment in which CD4 naive T cells are more prone to differentiate into Th2 phenotype is created due to the effect of CNI." (PMID 38409262, 2024). "To explore the mechanisms of decreased expression of PD-1 in CD4+ and CD8+ T cells from convalescent COVID-19 patients, we measured plasma cytokines associated with PD-1 expression, including IL-2, IL-6, IL-7, IL-10, IL-12p70, IL-33, IFN-γ and CCL19/MIP-3, by Luminex." (PMID 38424104, 2024). "Interestingly, activated CD4+ T cell subsets, including Th1, Th2, and Th17-like cells, demonstrated heightened proportions and greater clonal expansion in severe COVID-19 patients." (PMID 38392902, 2024). "This over-representation potentially suggests the importance of CD4 T cells in COVID-19 severity." (PMID 39705183, 2024). "The presence of anti-lymphocyte antibodies (ALAb) might play an important role in disease outcome, and more specifically in the lymphopenia observed in most COVID-19 patients, characterized by low numbers of CD4, CD8, and, to a lesser extent, B cells." (PMID 38694513, 2024).